SNHG1 (small nucleolar RNA host gene 1)
Diseases named in the same sentence as SNHG1 in open-access papers (continued):
Sharing a sentence is not in itself a finding about the gene and the disease.
tumor (continued). "Three studies including 232 patients reported the tumor stage based on different SNHG1 expression levels." (PMID 31008944, 2019). "It has been reported that SNHG1 can affect the growth of many kinds of tumor cells, whereas the precise role of SNHG1 in AML have not been clarified." (PMID 31615767, 2019). "SNHG1 level was correlated with tumor invasion depth (P = 0.035), distant metastasis (P = 0.024) and TNM stage (P = 0.006)." (PMID 30266084, 2018). "As revealed by our findings, the silencing of SNHG1 is capable of repressing the CCA tumor progression in vivo, suggesting the fact that SNHG1 performs a substantial function in CCA tumor proliferation." (PMID 29970899, 2018). "CDKN1A, one of the genes regulated by SNHG1 in accordance with the RNA-Seq, is capable of exhibiting the role of tumor suppressor genes in different kinds of cancer." (PMID 29970899, 2018). "Altogether, our results indicated that SNHG1 acts as molecular sponge for miR-154-5p, and the tumor-promoting effect of SNHG1 was partly dependent on sponging miR-154-5p." (PMID 30266084, 2018). "Our findings showed that SNHG1 expression was significantly increased in NSCLC tissues compared to adjacent non-tumor tissues (P < 0.05)." (PMID 28147312, 2017). "In the present study, we found that SNHG1 expression in NSCLC tissues was significantly increased compared to adjacent non-tumor tissues." (PMID 28147312, 2017). "In the present study, we found that lncRNA SNHG1 was increased in NSCLC tissues and cell lines, high expression of SNHG1 was correlated with larger tumor size, advanced TNM stage, lymph node metastasis and poor overall survival of NSCLC patients." (PMID 28147312, 2017). "The result showed that SNHG1 was higher expression in tumor tissues compared to normal tissues in CRC (P < 0.05)." (PMID 29340086, 2017). "Our study identified three androgen-responsive lncRNAs, LINC01138, SUZ12P1 and SNHG1 were significantly over-expressed in more metastasis and higher tumor stage patients." (PMID 27556357, 2016). "Whether SNHG1 can communicate with the tumor and bone microenvironment “soil” is a potential mechanism to reveal the role of PCa bone metastasis." (PMID 41507135, 2026). "Studies have found that SNHG1 can adsorb miRNAs and relieve their inhibitory effects on its target genes, thereby regulating processes such as proliferation, invasion, and metastasis of tumor cells." (PMID 41346419, 2025). "By contrast, tumor specimens showed a tighter, tumor-specific module: SNHG17 correlated strongly with SNHG1 (ρ = 0.61, p < 0.01) and with PABPC1L (ρ = 0.46, p < 0.05), while PABPC1L and SNHG1 were also significantly associated in tumor (ρ = 0.50, p < 0.01)." (PMID 41357316, 2025). "Tumor histological grade also correlates with SNHG1 expression, as more advanced grades/less differentiated tumors display greater expression levels of SNHG1, supporting the notion that increasing levels of SNHG1 might predict more aggressive tumors." (PMID 39200161, 2024). "Additionally, IHC results demonstrated a decrease in RRS1-positive cells in tumor tissues following SNHG1 knockdown." (PMID 38331968, 2024). "Moreover, SNHG1 plays an essential role in the processes of tumor cell proliferation, invasion, migration, and apoptosis." (PMID 37684619, 2023). "Reportedly, the lncRNA SNHG1 interacts with miR-101-3p to promote tumor progression." (PMID 40636922, 2023). "Furthermore, it summarizes the tumor-promoting mechanism of SNHG1 and the corresponding clinical significance and lists the abnormal expression of SNHG1 in tumor conditions reported in the past 5 years." (PMID 37684619, 2023).
tumor (continued). "However, different studies suggest that the carcinogenesis and tumor suppressor effects of SNHG1 in GC remain inconsistent." (PMID 37684619, 2023). "Similarly, all studied SNHGs are involved in EMT through activation of various athways including Notch-1, but in vivo experiments reveal a more crucial role in tumor growth and metastasis for SNHG1, SNHG3, SNHG5, SNHG12, and SNORA71A." (PMID 36139687, 2022). "SNHG1 has also been reported to reinforce anti-tumor properties of baicalein in the cervical cancer cell, affecting cell viability, migration, apoptosis, and tumor growth by regulating miR-3127-5p." (PMID 35246252, 2022). "While SNHG1 has been shown to regulate tumor growth, the biological function of LOC606724 in tumors is unknown." (PMID 34980213, 2022). "Additionally, SNHG1 was verified to facilitate tumor proliferation and repress apoptosis in vitro and in vivo." (PMID 36230661, 2022). "In vivo experiments showed that downregulation of SNHG1 inhibited tumor development in nude mice." (PMID 35141164, 2022). "Additionally, in vivo experiments showed that silencing SNHG1 hindered tumorigenesis and tumor growth." (PMID 36087568, 2022). "And SNHG1 contributed to the enhancement of drug resistance in tumor cells." (PMID 36087568, 2022). "Overexpression of MDM2 abrogated the effect of silencing SNHG1 on tumor growth." (PMID 36230661, 2022). "Finally, in vivo tumor formation and metastasis were evaluated to show the effect of the SNHG1-mediated miR-376a/FOXK1/Snail axis." (PMID 34095464, 2021). "Likewise, SNHG1 knockdown cells grew slower in compared with the control cohort, the average tumor volumes and weight in the ultimate experiment were significantly lower in the DU145/sh-SNHG1 cohort versus the negative control lentivirus vector cohort." (PMID 33542227, 2021). "This significant role in tumor progression may be explained by SNHG1’s ability to sponge four miRNAs with tumor-suppressive characteristics, i.e., miR-302, miR-372, miR-373, and miR-520." (PMID 33808624, 2021). "Also, plasma SNHG1 holds potential as a sensitive and reliable diagnostic marker of HCC because of its close correlation with tumor size and TNM stage." (PMID 34095464, 2021). "It is widely recognized that SNHG1 plays roles in cell proliferation and tumours." (PMID 33499863, 2021). "In addition, its high expression correlated with poor outcome of patients with HCC and advanced tumor stage, which was consistent with the findings reported by Zhang and his team, suggesting a prognostic value of SNHG1." (PMID 34095464, 2021). "SNHG1 knockdown exerts anti-tumor activity in HCC, suggesting a therapeutic target." (PMID 34095464, 2021). "We found that SNHG1 expression was upregulated in tumor tissues." (PMID 34806925, 2021). "In summary, our data demonstrate that SNHG1 plays crucial roles in tumor progression and may be a useful maker for OC prognosis." (PMID 33641229, 2021). "In addition, M2 polarization markers were also upregulated in tumor tissue of mice injected with cell mixture that SNHG1 was knockdown." (PMID 34618681, 2021). "Similarly, the number of tumor nodules in mice of the SNHG1 knockdown group was decreased compared with the NC group." (PMID 32497022, 2020). "However, the tumor volume and tumor increased with simultaneous interference with SNHG1 and overexpression of EZH2." (PMID 33194612, 2020). "Interestingly, several groups have recently reported that SNHG1 functions as a key regulator that modulates the progression of various tumours by competitively binding miRNAs." (PMID 32885590, 2020). "The authors performed an RNA transcriptome comparison between SNHG1 knockout and control cells and found differential expression of hundreds of transcripts, including the established tumor suppressor and EZH2 target CDKN1A, which showed significant upregulation upon SNHG1 knockout." (PMID 32331331, 2020). "SNHG1 can promote tumor growth by regulating the transcription of proximal and distal genes." (PMID 30728054, 2019).
tumor (continued). "Knocking down the expression of SNHG1 could reduce the tumor size and suppress cell proliferation and colony formation." (PMID 31691514, 2019). "In order to clarify the mechanism of SNHG1 promoting the malignant biological behavior of tumor by regulating miR-154-5p and miR-376b-3p, the overexpression and silence plasmids of miR-154-5p and miR-376b-3p were transfected into SNHG1 knockdown U87 and U251 cells." (PMID 30728054, 2019). "To determine whether the effect of SNHG1-mediated tumor cell proliferation via regulation of miR-145 is dependent on Dicer, we compared the effect of SNHG1 on the cell proliferation in parental HCT116 or HCT116 Dicer-/- cells." (PMID 29416759, 2018). "Several other lncRNAs have also been shown to function as oncogenes through sponging miRNAs and positively regulating their target tumor-promoting genes, including CCAT1, NEAT1, plasmacytoma variant translocation 1 (PVT1), small nucleolar RNA host gene 1 (SNHG1), UCA1, and XIST." (PMID 30223861, 2018). "Further analysis showed that the up-regulation of SNHG1 was positively associated with the tumor diameter, histological differentiation, TNM stage, lymph node metastasis, depth of invasion." (PMID 29340086, 2017). "Recent reports showed that SNHG1 play important roles in tumor progression." (PMID 28147312, 2017). "Our observation of strong tumor-specific co-expression among SNHG17, SNHG1 and PABPC1L; together with the reciprocal association between SNHG17 and RUSC1-AS1 in multivariable models suggest a model in which lncRNA networks and translation regulators act in concert to drive tumor cell phenotypes." (PMID 41357316, 2025). "Moreover, SNHG1 regulates tumor growth in vivo by regulating the miR-199a-3p/TFAM axis." (PMID 37684619, 2023). "Still, the oncogenic or tumor-suppressor role of SNHG1 in NB remains unclear." (PMID 36130928, 2022). "Besides, SNHG1 knockdown prevents tumor growth and metastasis of hepatocellular carcinoma." (PMID 35836822, 2022). "Similarly, SNHG1 lncRNA mediates tumor immune escape by affecting the differentiation of Tregs." (PMID 32083005, 2020). "In addition, Kaplan‐Meier analysis demonstrated a correlation between high tumor SNHG1 expression and reduced survival (including OS and DFS interval), suggesting that SNHG1 may be useful as a diagnostic and prognostic indicator in CRC patients." (PMID 31469189, 2019). "Collectively, these results indicate that SNHG17, PABPC1L and SNHG1 form a coordinated expression module in CRC samples and that RUSC1-AS1 is incorporated into this tumor-specific network." (PMID 41357316, 2025). "Our study identified a tumor-specific expression module comprising PABPC1L, SNHG17 and SNHG1, with RUSC1-AS1 incorporated into the tumor co-expression network." (PMID 41357316, 2025). "SNHG1 has been reported to promote CRC cell proliferation and invasion by sponging tumor-suppressive miRNAs, epigenetic regulation and modulating SMAD2 signaling." (PMID 41357316, 2025). "Similar trends were observed in the xenograft tumor model: both PTEN and USP8 protein levels were diminished in SNHG1 overexpressed tumor tissue, and these levels showed a positive correlation." (PMID 38365726, 2024). "Silencing SNHG1 inhibited M2 macrophage polarization by suppressing STAT6 phosphorylation, thereby inhibiting tumor growth and angiogenesis." (PMID 39676873, 2024). "Interestingly, aberrant expression of SNHG1 has been demonstrated to correlate significantly with a variety of important clinical characteristics in other forms of malignancy, including advanced tumor size, magnitude of vascular invasion, advanced TNM stage, and poorer differentiation." (PMID 39200161, 2024).
tumor (continued). "SNHG1 (Small Nucleolar RNA Host Gene 1): Identified in exosomes derived from CRC cells, SNHG1, a long non-coding RNA (lncRNA), suggests a potential role in intercellular communication and tumor–stroma immune interactions." (PMID 37760852, 2023). "The lncRNA SNHG1 regulates Treg cell differentiation through the miR-448/IDO pathway, affecting tumor immune escape, while specific Treg clearance can enhance the anti-tumor immune response." (PMID 37178254, 2023). "Given that better stability is an essential requirement for tumor biomarkers, the stability testing of LINC00265, LINC00467, UCA1, and SNHG1 in the isolated plasma exosomes was performed." (PMID 36276083, 2022). "For example, tumor-killing immune cells in the high expression group of SNHG16, SNHG6, SNHG11, FAM222A-AS1, RHPN1-AS1, SNHG1, and SNHG7 were significantly lower than those in the low." (PMID 35646635, 2022). "Further, we found significant relation between the aberrant upregulation of SNHG1 and SNHG3 in tumor grade and stage." (PMID 35592519, 2022). "Given that better stability is an essential prerequisite for tumor biomarkers, we sought to assess the stability of LINC00265, LINC00467, UCA1, and SNHG1 in the isolated plasma exosomes." (PMID 36276083, 2022). "LncRNAs regulate EMT process by targeting EMT-related signalling pathways directly (i.e., H19, HOTAIR, ZEB2-AS1, LincRNA-p21 and SNHG1), or function as ceRNAs (i.e., H19, HOTTIP, MALAT1, SNHG1 and SNHG6) for tumour suppressive miRNAs." (PMID 36310592, 2022). "The low expression group of SNHG16, SNHG6, SNHG11, FAM222A-AS1, RHPN1-AS1, SNHG1, and SNHG7 was accompanied by more immune cell infiltration, further supporting that PANoptosis plays a crucial role in the tumor immune microenvironment." (PMID 35646635, 2022). "Hence SNHG1 might be a tumor promoter and pro-metastatic lncRNA." (PMID 34095464, 2021). "Further experiments demonstrated that SNHG1 can interact with hnRNPL and ultimately leads to down-regulation of E-cadherin expression and promote EMT progression, leading to tumor metastasis in PCa." (PMID 33542227, 2021). "LncRNA-UCA1 and SNHG1 were significantly up-regulated in NSCLC tissues than in paired adjacent healthy tissues, and the up-regulation of UCA1 and SNHG1 promotes tumor progression." (PMID 32975291, 2020). "lnc-EGFR via regulating AP-1/NF-AT1/Foxp3 signaling pathway and lncRNA SNHG1 by regulating miR-448/IDO affect the differentiation and growth of immunosuppressive regulatory T cells (Tregs) and enable immune escape for tumor." (PMID 33281872, 2020). "Three molecules above form a ceRNA regulatory axis, in which our research prompts that SNHG1 possibly performed as sponge to provoke the effect of hsa-mir-145 on the up-regulation of SERPINE1, enhancing tumor cell migration and invasion." (PMID 33552958, 2020). "It was found that miR-101, an anti-tumor miRNA, was markedly upregulated in AML cells when SNHG1 was knocked down." (PMID 31615767, 2019). "NSCLC patients with high SNHG1 expression were significantly correlated with larger tumor size, advanced TNM stage, lymph node metastasis and poor overall survival than patients with low SNHG1 expression." (PMID 28147312, 2017). "A variety of studies have evaluated the correlation between SNHG1 expression and the clinicopathological characteristics of HCC patients, including tumor size, histological grade, presence of lymph node and distant metastases, disease stage (AJCC/BCLC), and AFP levels." (PMID 39200161, 2024). "Collectively, we speculated that PARP6 may act as a tumor suppressor in HSCC, which is a functional target of SNHG1." (PMID 35836822, 2022). "SNHG1 is upregulated in HCC, and the knockdown contributed to suppression of HCC cell viability, invasion, and migration properties and promotion of apoptosis, exerting anti-tumor activity in HCC." (PMID 35693941, 2022). "Our findings reveal that SNHG1 is a key regulator in HSCC and may contribute to tumor development via targeting PARP6." (PMID 35836822, 2022).
tumor (continued). "Serum small EV‐derived MALAT1, DLEU2, HOTTIP, and SNHG1 were significantly highly expressed in patients with HCC and showed good to excellent discriminating capacity that was significantly higher than that of the traditional tumor marker AFP." (PMID 34185961, 2021). "The key role of the SNHG1/miR-140/TLR4/NF-κB signaling axis in CCA tumorigenesis and progression has been established, indicating that TLR4 expression promotes cell proliferation and angiogenesis and inhibits apoptosis, stimulating tumor invasion and metastasis." (PMID 37345131, 2023). "SNHG1 competitively binds to miR-376a and inhibits the expression of miR-376a, thereby promoting FOXK1 and Snail expression, leading to reduction of HCC cell proliferative, migrating, and invasive properties, and promotes cell apoptosis and promotion of tumor growth and metastasis in HCC." (PMID 34095464, 2021). "In addition, the RIP experiments confirmed that SNHG1 and miR-154-5p or miR-376b-3p existed in the RISC complex, and the study of SNHG1 as a miRNAs sponge binding to miRNAs and affecting the biological behavior of tumor cells has also been sighted in some reports." (PMID 30728054, 2019). "Collectively, our data demonstrate that SNHG1 is able to promote the progression of AML, at least in part, through negative modulation of anti-tumor miR-101." (PMID 31615767, 2019). "SNHG1 expression is only related with TNM stage and lymph node metastasis, but not tumor size, tumor subtype, or patient gender." (PMID 31480503, 2019).
neurodegenerative disease (4 papers, 2023 to 2025). A disorder of the central nervous system characterized by gradual and progressive loss of neural tissue and neurologic function. "Dysregulated lncRNAs upon WS treatment included BACE1-AS, MALAT1, SNHG1, HOTAIR, MEG3, BDNF-AS, and SHANK2-AS1 which are potential biomarkers in several neurodegenerative diseases." (PMID 40928594, 2025). "The lncRNA small nucleolar RNA host gene 1 (SNHG1) has been shown to regulate several pathobiological mechanisms including neuroinflammation, DNA methylation, and apoptosis in neurodegenerative diseases including AD." (PMID 39199508, 2024).
infection (3 papers, 2020 to 2025). The state of being infected such as from the introduction of a foreign agent such as serum, vaccine, antigenic substance or organism. "The abundance of the spliced isoform of SNHG1 was sharply increased over the course of infection, whereas the unspliced precursor was either unchanged or slightly decreased." (PMID 39869630, 2025). "The silencing of SNORA/Ds encoded within RPS11 (SNORD35B), SNHG3 (SNORA73A, SNORA73B), and SNHG1 (SNORD22, SNORD25, SNORD26, SNORD27, SNORD28, SNORD29, SNORD30, SNORD31) inhibited infection with influenza A virus." (PMID 36430145, 2022).
bladder (2 papers, 2018 to 2024). "Though SNHG1 was significantly elevated in both BBNtreated mouse urothelium and human MIBCs, the molecular mechanisms underlying SNHG1’s role in bladder carcinogenesis remain largely uncharted." (PMID 38365726, 2024).
cardiac diseases (2 papers, 2020 to 2024). "As miR-195 reportedly negatively regulates expression of BCL-2-like protein 2 (BCL2L2), modifying the level of SNHG1 might constitute a novel strategy for treating cardiomyocyte apoptosis-related heart diseases." (PMID 31942979, 2020).
colorectal (2 papers, 2020 to 2021). "KCNQ1OT1 and SNHG1 possessed hub nodes properties in all of the four context-specific ceRNA networks, implying significant potential in regulating colorectal carcinogenesis." (PMID 33194594, 2020).